SDC4 (syndecan 4)
Diseases named in the same sentence as SDC4 in open-access papers (continued):
Sharing a sentence is not in itself a finding about the gene and the disease.
ovarian carcinoma (12 papers, 2012 to 2025). A malignant neoplasm originating from the surface ovarian epithelium. "By using TGCA datasets, we found that SDC4 was up-regulated in the ovarian cancer tissues and high expression of SDC4 in ovarian cancer tissues was associated with shorter overall survival of patients with ovarian cancer." (PMID 40416874, 2025). "We found that high expression of SDC4 was associated with shorter overall survival of patients with ovarian cancer." (PMID 40416874, 2025). "Malignant cells isolated from the ascites of patients with ovarian cancer were enriched in NK clusters presenting high levels of the CCL5 gene, whose expression was deficient in ovarian cancer cells that expressed high levels of SDC4." (PMID 34680190, 2021). "In contrast, for periostin, loss of both Syndecan-1 and Syndecan-4 negatively affects ovarian cancer cell adhesion, which supports the notion that periostin utilizes a distinct mode of cellular interaction." (PMID 22640878, 2012). "Validation using TCGA datasets revealed upregulation of SDC4 in ovarian cancer tissues, with high SDC4 expression correlating with shorter overall survival." (PMID 40416874, 2025). "qRT-PCR analysis confirmed a significant upregulation of SDC4 in ovarian cancer cell lines compared to control samples." (PMID 40416874, 2025). "The qRT-PCR validation further corroborated our bioinformatics predictions, showing a significant upregulation of SDC4 expression in ovarian cancer cell lines, particularly in OVCAR3 and SKOV3, relative to control cells." (PMID 40416874, 2025). "The 3.8- to 4.2-fold increase in SDC4 expression was observed in ovarian cancer tissues compared to normal ovarian tissues, serving as the baseline for this comparison." (PMID 40416874, 2025). "The ovarian cancer cell type was classified into SDC4 high expression and SDC4 low expression groups." (PMID 40416874, 2025). "The expression level of SDC4 was significantly higher in the ovarian cancer tissues than that in the normal ovarian tissues." (PMID 40416874, 2025). "Our findings offer new insights into the molecular mechanisms governing the TME of HGSOC, although further investigation is needed to fully elucidate the functional role of SDC4 in ovarian cancer progression." (PMID 40416874, 2025). "LncRNA WDFY3-AS2 promotes cisplatin resistance and the cancer stem cell in ovarian cancer by regulating hsa-miR-139-5p/syndecan 4 (SDC4) axis." (PMID 35412951, 2022). "The migration, invasion and tumor growth of ovarian carcinoma is mediated by the carbohydrate modifications of proteoglycans.SDC4 is upregulated in ovarian carcinoma." (PMID 34282767, 2021). "Notably, we observed that high expression of SDC4, a critical component of PTN signaling, is significantly associated with poor prognosis in ovarian cancer patients, highlighting its potential as a prognostic biomarker." (PMID 40416874, 2025). "The expression of SDC4 in ovarian cancer tissues was further analyzed using GEPIA tool." (PMID 40416874, 2025). "Finally, the prognostic role of SDC4 in HGSOC was further evaluated using TCGA datasets, which demonstrated that high SDC4 expression is associated with poor patient prognosis in ovarian cancer." (PMID 40416874, 2025). "SDC4 was also found to be overexpressed in ovarian cancer and fibrosarcoma." (PMID 37954130, 2023). "Moreover, WDFY3-AS2 can upregulate SDC4 expression to promote cisplatin resistance in ovarian cancer, and si-WDFY3-AS2 reduces the invasion and migration of tumor cells." (PMID 35273128, 2022). "Many cells express SDC4, which has been reported to influence ovarian carcinoma cells." (PMID 34051810, 2021). "Moreover, SDC4 expression correlated with poor overall survival in ovarian cancer patients." (PMID 40416874, 2025). "Furthermore, WDFY3-AS2 also could promote cisplatin resistance by the expression of miR-139-5p/SDC4 in ovarian cancer, which may provide a promising drug target to drug resistance." (PMID 36217201, 2022).
ovarian carcinoma (continued). "Thus, for ovarian cancer cells, it appears neither Syndecan-1 nor Syndecan-4 is necessary for adhesion to TGFBI, nor does the loss of Syndecan-4 synergize with αvß3 to stimulate adhesion to TGFBI." (PMID 22640878, 2012). "qRT-PCR validation confirmed a significant upregulation of SDC4 in OVCAR3 and SKOV3 ovarian cancer cell lines, with expression levels 3.8- to 4.2-fold higher than control cells (p<0.01), supporting the computational predictions." (PMID 40416874, 2025). "Although each alteration is infrequent, ROS1 fusions with many kinds of 5′ partner genes (CCDC6, CD74, EZR, KDELR2, LRIG3, SDC4, SLC34A2 and TPM3) have been reported in lung, brain, biliary tract, and ovarian cancers." (PMID 23418494, 2013).
atherosclerosis (11 papers, 2015 to 2025). A disease characterized by the build-up of fatty material and calcium deposition in the arterial wall resulting in partial or complete occlusion of the arterial lumen. "Reports suggest that there is a substantial increase in syndecan-4 expression following prolonged exposure to low shear stress, a condition often associated with atherosclerosis development." (PMID 38562144, 2024). "On the other hand, it was also reported that, besides T-cell activation state, various pathophysiological conditions, including bacterial endotoxin shock, acute pneumonia, Helicobacter pylori infection, atherosclerosis and ischemic heart disease, are associated with SDC-4 expression levels in PBMCs." (PMID 28116121, 2016). "In this context, SDC4 is likely to be a suitable biomarker for the early prediction of subclinical atherosclerosis in AS patients." (PMID 38241528, 2024). "Previous research has indicated that low levels of SDC4 in macrophages promotes atherosclerosis by polarizing macrophages toward a more proinflammatory state." (PMID 37991018, 2023). "The results revealed that a reduction of SDC4 in macrophages promotes atherosclerosis by aggravating the proinflammatory capacity of macrophages." (PMID 35842658, 2022). "Regarding PGs, it is postulated that their expression in atherosclerosis depends on the balance between the expressions of syndecan-1 and syndecan-4." (PMID 33997316, 2021). "In conclusion, our results suggest that miR-126 (i) is overexpressed by long-term LSS, (ii) has a role in up- and downregulation of genes involved in atherosclerosis, and (iii) affects SDC-4 expression." (PMID 26221595, 2015). "Herein, we aimed to investigate the role of SDC4 in subclinical atherosclerosis in AS patients." (PMID 38241528, 2024). "This linkage could have implications for atherosclerosis development, particularly through syndecan-4." (PMID 38562144, 2024). "For example, if the increase in the expression of syndecan-1 is lower than that in the expression of syndecan-4 in neointimal smooth muscle cells, atherosclerosis progression influenced by the imbalance between the expressions of syndecan-1-syndecan-4 can be accelerated." (PMID 33997316, 2021). "Therefore, this study investigated the role of SDC4 in subclinical atherosclerosis in AS patients." (PMID 38241528, 2024). "Crosstalk occurring between syndecan-1 and syndecan-4 expressions, i.e., upregulation of syndecan-4 expression by downregulation of syndecan-1 expression under certain conditions in atherosclerosis may be one of the factors responsible for atherosclerosis progression." (PMID 33997316, 2021). "Given that in our study syndecan-4 correlated with geometrical echocardiographic parameters and LVH, we can hypothesized that elevated syndecan-4 may reflects the severity of defense mechanisms against ischemia induced myocardial damage as well as may atherosclerosis." (PMID 27685148, 2016).
diabetes (11 papers, 2011 to 2025). "The syndecan-4 shedding during chronic inflammation caused by diabetes mellitus resulted in an impaired macrovascular angiogenesis." (PMID 32133006, 2020). "It attenuated the increase in Sdc4 mRNA expression observed in diabetes by 1.5-fold and restored the loss of glomerular SDC4 protein expression by 1.8-fold." (PMID 32037077, 2020). "In this study, we investigated our hypothesis that GEC glycocalyx dysfunction in diabetes is caused by MMP-mediated SDC4 shedding, and importantly, that it is amenable to therapeutic intervention." (PMID 32037077, 2020). "We hypothesize that GEC glycocalyx dysfunction in diabetes is caused by MMP-mediated shedding of SDC4 and that this is amenable to therapeutic intervention." (PMID 32037077, 2020). "The TNFα mediated shedding of syndecan-4 could well be the reason for the defective angiogenesis during inflammation caused by diabetes mellitus." (PMID 32133006, 2020). "High syndecan-4 patients were older (p<0.001),more often had a history of MI (p < 0.001), had higher prevalence of diabetes mellitus (p = 0.012), and were more likely to be on beta blocker therapy (p = 0.001)." (PMID 27685148, 2016). "Changes in the proteoglycans glypican and syndecan-4 have been reported in several pathological conditions, but little is known about their expression in the heart during diabetes." (PMID 21518435, 2011). "The increased amount in diabetes of glypican-1 and syndecan-4 is somewhat expected, because these proteoglycans modulate the interaction of FGF, augmented in diabetes, with different receptors and protect it against inactivation." (PMID 21518435, 2011). "In our study, after diabetes induction, an increase occurred in syndecan-4 mRNA and protein expression in skeletal muscle." (PMID 21518435, 2011). "Controlling insulin secretory function by regulating the Sdc4 gene expression may also be a target for diabetes therapy." (PMID 36292936, 2022). "Delivery exogenous syndecan-4 could improve angiogenic therapy for ischemia in diabetes; on the contrary, decreasing the expression of syndecan-4 on the cell surface remarkably inhibited the adhesion and migration of endothelial progenitor cells 30,31." (PMID 34790051, 2021). "In addition, tests in mice demonstrated inhibition of the syndecan-4 shedding process attenuated diabetes-induced kidney injury in the early stage." (PMID 33879092, 2021). "Blockade of MMP2 and -9 attenuated diabetes-induced changes in glomerular endothelial glycocalyx Sdc4 and glomerular SDC4 at the mRNA and protein levels, suggesting a reduction in glomerular endothelial SDC4 shedding." (PMID 32037077, 2020). "The aim of this study was to investigate in vivo heart function changes and alterations in mRNA expression and protein levels of glypican-1 and syndecan-4 in cardiac and skeletal muscles during streptozotocin (STZ)-induced diabetes." (PMID 21518435, 2011). "Sdc4 mRNA expression was upregulated 2.5-fold, whereas Sdc1 mRNA expression was not significantly changed in diabetes." (PMID 32037077, 2020). "The increased level of syndecan-4 specific protein after diabetes induction was not paralleled by the mRNA expression in cardiac cells." (PMID 21518435, 2011). "For this purpose, we examined the mRNA expression and the amount of 2 key cell surface heparan sulfate chain-carrying core proteins, syndecan-4 and glypican-1, after 24 hours, 10 days, and 30 days of STZ-induced experimental diabetes in 2 muscles, cardiac and skeletal." (PMID 21518435, 2011). "SDC4 is unlikely to be the only constituent that is being shed from the glycocalyx in diabetes." (PMID 32037077, 2020). "In a mouse model of slowly progressive diabetes that does not show hyperglycemia until four weeks following low doses STZ administration, SDC4-KO mice showed hyperglycemia from four days after STZ administration and reduced casual insulin secretion and pancreatic β-cell mass." (PMID 36292936, 2022).
diabetes (continued). "Similarly, SDC4 expression by enzyme-linked immunosorbent assay (ELISA) was reduced 1.6-fold in diabetic glomeruli, suggesting glomerular SDC4 shedding, whereas SDC1 glomerular protein expression was not changed in diabetes." (PMID 32037077, 2020).
osteosarcoma (9 papers, 2017 to 2024). A usually aggressive malignant bone-forming mesenchymal neoplasm, predominantly affecting adolescents and young adults. "Increased SDC4 expression is associated with the formation of distant metastasis and increased tumor size in osteosarcoma." (PMID 34282767, 2021). "Mechanistically, syndecan-4 mediates tumorigenic properties of osteosarcoma cells via cell surface interactions with autotaxin-β." (PMID 33810567, 2021). "Increased SDC4 expression is related to the existence of distant metastasis and increased size of the tumor mass in osteosarcoma, but increased patient survival in renal cell carcinoma." (PMID 34282767, 2021). "A study has shown that syndecan-4 expression is upregulated in high-grade osteosarcoma when compared to other tissues." (PMID 33810567, 2021). "We notably found that a pretreatment with anti-SDC4 antibodies and silencing of SDC4 expression totally abolished human osteosarcoma MG63 cell proliferation induced by exogenous ATXβ." (PMID 31906151, 2019). "Thus, the syndecan-4 mediated mechanotransduction pathway is likely to be broadly important in cancer, as the expression of syndecan-4 is high in cancers such as glioblastoma and osteosarcoma, and the high expression correlates with reduced survival." (PMID 36693448, 2023). "Recently, it was demonstrated that the prometastatic integrin-interacting factor autotaxin-beta promotes osteosarcoma cell proliferation via a mechanism that requires a physical interaction with syndecan-4, expanding the range of mechanisms by which syndecan-4 regulates tumor cell growth." (PMID 33810567, 2021). "SDC4 regulates autotaxin-β induced proliferation in osteosarcoma." (PMID 34282767, 2021). "In addition, exogenous ATXβ-induced MG63 osteosarcoma cell proliferation required physical interaction of ATXβ with the cell surface via an SDC4-dependent mechanism." (PMID 30237860, 2018).
heart failure (8 papers, 2014 to 2025). Inability of the heart to pump blood at an adequate rate to meet tissue metabolic requirements. "The serum levels of shed soluble syndecan-1 and syndecan-4 have been proven to be associated with various diseases, such as sepsis, ischemia–reperfusion injury, multiple types of cancer, pneumonia, and heart failure." (PMID 41357480, 2025). "In contrast, soluble syndecan-4 in serum was primarily associated with pneumonia and heart failure." (PMID 41357480, 2025). "Supporting exacerbated heart failure, there was increased expression of Nppa in the LV and RV of Sdc4-Tg mice compared to WT after AB, and increased expression of Nppb in the RV." (PMID 36205855, 2022). "Studies with larger number of patients are required to determine the influence of ethnicity on the predictive role of syndecan-4 as a biomarker for heart failure of different etiologies." (PMID 29232393, 2017). "Serum syndecan-4 levels are elevated in patients with heart failure, increase in proportion with LV mass, and correlate with LV geometrical parameters, suggesting it could have value as a blood biomarker." (PMID 36205855, 2022). "Although dephosphorylation of syndecans is less well understood, we have previously found that dephosphorylation of syndecan-4 might work as a molecular switch in the progression toward heart failure." (PMID 32984315, 2020). "Our findings of the association between syndecan-4 SNP rs1981429 with hypertension and CAD are interesting, because serum syndecan-4 concentration has shown promise as a novel diagnostic and prognostic biomarker for heart failure." (PMID 25410619, 2014). "Furthermore, high serum levels of syndecan-4 had been identified as a significant predictor of heart failure in hypertensive patients, and syndecan-4 was also considered a suitable biomarker for adverse left ventricular remodeling in patients with dilated cardiomyopathy." (PMID 41357480, 2025). "Indeed, the studies evaluating syndecan-4 as a heart failure biomarker published so far include mostly Asians or Caucasian populations, and data from mixed, and afro-descendent populations, such as the one included in our study, cannot be found in the literature." (PMID 29232393, 2017). "Additionally, Takahashi and colleagues assessed the concentration of syndecan-4 in 45 subjects with heart failure and 21 healthy subjects, finding also a moderate and negative correlation between syndecan-4 and LVEF, suggesting that, like NT-ProBNP, it might be a useful biomarker for heart failure." (PMID 29232393, 2017).